TRPV1 (transient receptor potential cation channel subfamily V member 1)
Diseases named in the same sentence as TRPV1 in open-access papers (continued):
Sharing a sentence is not in itself a finding about the gene and the disease.
infection (continued). "We lesioned TRPV1+ neurons with RTX 4 weeks prior to infection, and DRG immunofluorescence suggested a significant reduction in TRPV1+ neurons." (PMID 38129779, 2023). "The authors showed that BALB/c mice produce lower levels of Bdk in response to infection than C57BL/6 mice and mention other studies that show that BALB/c mice have lower levels of TRPV1 expression in some sets of sensory neurons." (PMID 35604095, 2022). "To evaluate the role of TRPV1 and TRPV4 on pneumococcal invasive diseases, we established a spontaneous pneumococcal lethal infection model after nasal colonization." (PMID 34804016, 2021). "In the mono-infection model, the levels of TNF-α were significantly higher in TRPV4 KO mice than those of wild type and TRPV1 KO mice (p < 0.05 and p < 0.001, respectively)." (PMID 34804016, 2021). "Up-regulation of TRPV1, TRPA1 and ASICS3 expression occurred by 12 hours post-infection in each cell type." (PMID 28187208, 2017). "To determine if the findings in BEAS-2B cells were representative of primary human bronchial epithelial cells we examined TRPV1 and ASICS3 mRNA levels after infection of PBEC with RSV or MV as before." (PMID 28187208, 2017). "RSV induced a 15-fold increase in TRPV1 and almost 30-fold increase in ASICS3 mRNA in BEAS-2B cells, respectively, at 12 hours post infection (hpi)." (PMID 28187208, 2017). "We performed preliminary experiments to determine if MV and RSV infection induced TRPV1 and ASIC3 channel mRNA up-regulation in BEAS-2B and SHY5Y5 cells was related to the inoculum titre and/or duration of infection." (PMID 28187208, 2017). "We demonstrate here that the infection with MV and RSV in BEAS-2B epithelial and SHSY5Y neuronal cells induces significant up-regulation of TRPV1 and ASIC3 mRNA levels compared to mock-infected cultures." (PMID 28187208, 2017). "Moreover, the functional expression of TRPV1 on macrophages is involved in the replication of CHIKV in these cells and cytokine production following infection." (PMID 40001474, 2025). "In conclusion, our study illustrates that TRPV1+ neurons inhibit neutrophil recruitment and modulate macrophage polarization by releasing CGRP in response to S. aureus infection, leading to exacerbation of local infection." (PMID 38129779, 2023). "Infection induced changes in adhesion molecule expression were not global, as MAdCAM-1+ BECs were not different in WT or TRPV1-/- mice." (PMID 38109366, 2023). "TRPM8 has been shown to antagonize TRPV1, and thus we hypothesize that stimulating TRPM8 blocks TRPV1-mediated mitochondrial fragmentation following CVB exposure and attenuates infection." (PMID 32231022, 2020). "Following S. aureus infection, RTX-treated mice did not display drops in thermal latencies, indicating that TRPV1+ neurons are critical for heat hyperalgesia during infection." (PMID 29295977, 2018). "Surface labelling of TRPA1 after shRNA treatment was performed similarly except using TGNs not subjected to infection with lenti TRPV1-DsRed." (PMID 26888187, 2016). "A physiological/pathophysiological role for non-neuronal TRPV1 is perhaps nowhere more apparent than in the case of inflammation, infection and immunity." (PMID 23800232, 2013). "While future studies are warranted for determining whether neuronal ALKAL2 participates in the inflammatory response, it is plausible that, upon activation, peptidergic TRPV1 nerve endings release ALKAL2 at the periphery, thus contributing to skin and mucosal host responses to infection or injury." (PMID 35608912, 2022). "Because high temperature facilitates TRPV1 activation, and we saw that transient hyperthermia amplified CVB infection, we investigated whether treating cells with the selective TRPV1 inhibitor SB-366791 would alter infection." (PMID 32231022, 2020).
peripheral neuropathy (34 papers, 2007 to 2026). A disorder affecting the peripheral nervous system. "And ropivacaine can affect peripheral neuropathy in streptozotocin-diabetic rats via TRPV1-CGRP pathway." (PMID 39619328, 2024). "Assessing localization of the transient receptor potential vanilloid-1 (TRPV1) in skin nerve fibers is crucial for understanding its role in peripheral neuropathy and pain." (PMID 39557902, 2024). "As trauma-induced peripheral neuropathy for example, mechanical stress transferred its signaling into several stress sensor protein, such as TRPV1 and TRPA149." (PMID 36438920, 2022). "The functions of TRPV1 are regulated by the TRPV1-tubulin complex on the membrane and sub-membranous regions in chemotherapy-induced peripheral neuropathy." (PMID 34638704, 2021). "Previous in vivo studies have reported that AMG9801 and NEO6860 improved paclitaxel-induced peripheral neuropathy by inhibiting the function of TRPV1." (PMID 33806325, 2021). "TRPV1 was also shown to be involved in the pathogenesis of chemotherapy-induced peripheral neuropathy." (PMID 32570786, 2020). "This study investigated the involvement of TRPV1 in the spinal cord in PTX-induced painful peripheral neuropathy." (PMID 32570786, 2020). "In contrast, the TRPV1 siRNA group showed a significant decrease in PTX-induced peripheral neuropathy at day 14 compared to the siRNA-negative control group." (PMID 32570786, 2020). "Peripheral neuropathy is known to produce a wide variety of changes in TRPV1 expression in sensory ganglia." (PMID 32404326, 2020). "Evidence suggests that TLR4 promotes TRPV1 overexpression in DRG neurons during paclitaxel-induced peripheral neuropathy and inflammation." (PMID 31775332, 2019). "Despite these known effects, the importance of TRPV1 in the pathogenesis of NP or peripheral neuropathies remains controversial." (PMID 28321335, 2017). "It has been shown that TRPV1 expression in nociceptive DRG neurons is increase in peripheral neuropathy in rodents." (PMID 27064319, 2016). "We, therefore, proposed that siRNA targeting TRPV1 would prevent PTX-induced peripheral neuropathy." (PMID 32570786, 2020). "In this study, we used a mouse model to investigate whether TRPA1, TRPM8, and TRPV1 are involved in the oxaliplatin-induced acute peripheral neuropathy." (PMID 22839205, 2012). "Indeed, when used as a topical analgesic, capsaicin's mechanism of action involves the selective and reversible defunctionalization of cutaneous sensory nerve endings expressing TRPV1, which have been shown to be hyperactive in painful peripheral neuropathies." (PMID 20937130, 2010). "The present study investigated the roles of TRPV1 cation channels, which are highly expressed in DRG neurons in OX-IN peripheral neuropathy, and focused on the basic mechanisms of this neurotoxicity." (PMID 40124779, 2025). "This also reduced protein kinase C epsilon type (PKCε) and transient receptor potential cation channel subfamily V member 1 (TRPV1) in the spinal cord and DRG of paclitaxel-induced peripheral neuropathy rats and mice." (PMID 35566252, 2022). "Toll-like receptors (TLR-1, TLR-2, and TLR-4) and the transient receptor potential family of ion channels (TRPV1 and TRPV4) have been discovered, demonstrating their active role in chemotherapy-induced peripheral neuropathy." (PMID 35956877, 2022). "This was also verified using STZ-induced diabetic rats, suggesting that activation of TRPV1 and the release of CGRP participate in diabetic vascular disease, and circulatory function directly affects peripheral neuropathy progress." (PMID 31661547, 2019). "A majority of reports dispute the involvement of these entities in neuropathic mechanical allodynia: knock-out or knock-down of TRPV1 does not affect mechanical hyperalgesia following peripheral neuropathy in mice." (PMID 32404326, 2020). "Moreover, antioxidants such as quercetin were able to inhibit TRPV1 and PKC activations in a study of paclitaxel-induced peripheral neuropathy." (PMID 29491840, 2018).
peripheral neuropathy (continued). "Niflumic acid is also a TRPV1 channel antagonist and it was reported that peripheral neuropathy by suppressing excessive ROS, RNS, inflammatory cytokine production and TRPV1 activation in neuropathic pain-induced rats were recovered by the niflumic acid treatment." (PMID 29491840, 2018). "Furthermore, oxaliplatin had no rapid-onset effect on capsaicin-evoked nocifensive behaviors or the number of capsaicin-sensitive DRG neurons, suggesting that oxaliplatin-induced acute peripheral neuropathy is not mediated by TRPV1." (PMID 22839205, 2012).
inflammation (29 papers, 2010 to 2026). Aberrant reaction of the microcirculation characterized by movement of fluid and leukocytes from the blood into extravascular tissues. "In conclusion, intestinal inflammation is associated with an overexpression of TRPV1 and S100β in enteric glia and astrocytes along the gut–brain axis, which is involved in pain establishment." (PMID 34829900, 2021). "Capsaicin is a capsaicinoid that causes a cutaneous neurogenic inflammation after activation of the vanilloid receptor subtype 1 (TRPV1) with generation of substance P (SP) and calcitonin gene related peptide (CGRP) and release of proinflammatory mediators, such as BK, histamine, 5-HT, and PG." (PMID 27916942, 2016). "This alludes to the fact that activation of pancreatic TRPV1-positive nociceptive neurons contributes to neurogenic pancreatic inflammation." (PMID 41596312, 2026). "Over the course of 7 days, DSS-treated TRPV1-hM4Di mice developed intestinal inflammation characterized by a slight decrease in the body weight, increase in macroscopic damages and production of pro-inflammatory cytokines TNF-α, IL1-β, and IL-6." (PMID 34954381, 2022). "Cutaneous TRPV1 channels have been primarily involved in temperature sensing, modulating skin barrier function, and in neurogenic inflammation, pain an pruritus." (PMID 33420359, 2021). "During bladder inflammation or spinal cord injury, TRPV1, substance P and CGRP expression is elevated and this allows for the development of bladder overactivity and pain." (PMID 27322240, 2016). "The enhancement of TRPV1 upregulation has also been reported in TG neurons following tooth pulp inflammation." (PMID 23341909, 2013). "Both TRPV1 and TRPA1, members of the TRP channel superfamily, play a key part in lung inflammation via the release of neuropeptides (substance P) and proinflammatory factors, such as leukotriene, IL-1α, and TNF-α, which cause primary airway inflammation." (PMID 37836429, 2023). "Therefore, we speculate that increased ROS formation by Nox4 may enhance the function of tubular TRPV1 in terms of renal inflammation." (PMID 34201387, 2021). "It is highly probable that TRPV1 and TRPA1 will be activated simultaneously during episodes of airway inflammation." (PMID 31170994, 2019). "The overall effect of DEP is neurogenic inflammation through release of substance P and neurokinin A (mediated by TRPA1 and TRPV1) and through production of cytokines and chemokines (mediated by TRPV1 and TRPM8), and variations in TRPA1 activation promote differences in lung inflammation and injury." (PMID 33803491, 2021). "Transient receptor potential (TRP) vanilloid 1 (TRPV1) and ankyrin 1 (TRPA1) both may play important roles in lung inflammation and AHR." (PMID 31281589, 2019). "There is evidence of increased expression of TRPV-1 in the airway nerves of patients with unexplained chronic cough, and a recent study showed that airway inflammation can initiate the expression of TRPV1 and TRPA1 in airway afferent neurons that normally do not express these ion channels." (PMID 23552099, 2013). "Here, we show that luteolin antagonized the Ca2+ elevation response to icilin in TRPM8-HEK293 cells, without activating or inhibiting TRPV1- or TRPA1, the main TRP channels involved in gut inflammation." (PMID 40280909, 2025).
neurodegenerative disease (19 papers, 2016 to 2025). A disorder of the central nervous system characterized by gradual and progressive loss of neural tissue and neurologic function. "Because TRPV1 has shown strong associations with the pathogenesis of neurodegenerative diseases, TRPV1 agonists and antagonists are becoming promising therapeutic targets." (PMID 38202764, 2023). "Here, we emphasize the cannabinoid receptor type 2 (CB2) and the transient receptor potential vanilloid type 1 (TRPV1) channel, both implicated in neurodegenerative diseases and pain." (PMID 35281260, 2022). "It is therefore likely that TRPV1 activation by CAP has therapeutic potential for treating neurodegenerative diseases, that are associated with neuroinflammation and oxidative stress, such as PD." (PMID 29968707, 2018). "TRPV1 agonists are also increasingly being a promising avenue in managing chronic conditions, particularly neurodegenerative diseases." (PMID 39965247, 2025). "We here summarize the current understanding of TRPV1’s effects and its agonists and antagonists as a therapeutic means in neurodegenerative diseases, and highlight future treatment strategies using natural TRPV1 agonists." (PMID 38202764, 2023). "Recently, it has been shown, that TRPV1 channels are involved in the generation of pain which accompanies neurodegenerative diseases." (PMID 33802055, 2021). "Moreover, TRPV1 has shown robust pathogenetic correlation with neurodegenerative diseases, particularly Alzheimer's disease, Parkinson's disease and multiple sclerosis, through the regulation of neuroinflammation." (PMID 39965247, 2025). "Thus, TRPV1 activation‐induced autophagy is more likely to be beneficial in neurodegenerative diseases." (PMID 37641913, 2024). "Therefore, modulators of TRPA1 and TRPV1 have the potential for the development of new therapeutic agents for the treatment of neurodegenerative diseases." (PMID 38203538, 2023). "Accumulating evidence has suggested that TRPV1 is closely related to immune responses and might be recognized as a molecular switch in the neuroinflammation of the majority of neurodegenerative diseases." (PMID 38202764, 2023). "Therefore, these modulators of TRPA1 and TRPV1 have the potential for the development of new therapeutic agents for neurodegenerative disease treatment." (PMID 38203538, 2023). "In neurodegenerative disease, native TRPV1 may tune NaV expression in neurons under stress to match excitability to available metabolic resources." (PMID 32273850, 2020). "TRPV1 control of cellular response against oxidative environments to improve cell survival may lead to progress in stem cells graft, organ transplant, ischemia reperfusion disorders and neurodegenerative disease." (PMID 32528302, 2020). "Transient receptor potential vanilloid 1 (TRPV1), also known as the capsaicin receptor, is a ligand-gated nonselective cation channel with Ca2+ permeability, and has neuroprotective effects against neurodegenerative diseases." (PMID 39468688, 2024). "Transient receptor potential vanilloid type 1 (TRPV1) channels are nonselective cation channel protein that have been proposed as neuroprotective targets in neurodegenerative diseases." (PMID 35599331, 2022). "Transient receptor potential vanilloid 1 (TRPV1) channels are nonselective ligand-gated cation channels that have been proposed as neuroprotective targets in neurodegenerative diseases such as Alzheimer’s disease and PD." (PMID 35599331, 2022).
cardiovascular diseases (14 papers, 2013 to 2026). "Moreover, treating chronic pain patients with TRPV1 antagonists may produce untoward side effects, such as hyperthermia, increased susceptibility to cardiovascular diseases, etc.." (PMID 24708859, 2014). "In the context of cardiovascular disease, TRPV1 is rather protective against atherosclerotic plaque formation by reducing lipid storage and diminishing endothelial cell inflammation but also has proapoptotic characteristics." (PMID 34169069, 2021). "Although several TRPV1 agonists are commonly used for pain relief, the potential of TRPV1 analogues in the treatment of cardiovascular diseases is just emerging." (PMID 34040539, 2021). "b) TRPV1 and cardiovascular disease: TRPV1 is highly expressed in the smooth muscles of coronary arterioles, skeletal muscles, adipose tissue, and microvessels (vasa vasorum)." (PMID 34779356, 2021). "Several TRPV1 agonists are routinely used for pain relief, but the potential use of TRPV1 analogues in the treatment of cardiovascular diseases is just emerging." (PMID 34564577, 2021). "The results indicate that activation of the TRPV1 channel can modulate cardiovascular responses and that these channels can be a promising target for the treatment of cardiovascular disease." (PMID 31496955, 2019). "Recently, convergent sets of evidence support a physiological role for TRPV1 as a crucial integrator in the functions of the cardiovascular system and in cardiovascular diseases." (PMID 23878415, 2013). "The latest reviews also indicate that an increasing number of studies are targeting TRPV1 and TRPV2 channels as therapeutic targets for cardiovascular diseases." (PMID 39742020, 2024). "In addition, non-neuronal TRPA1 and TRPV1 play a role in cardiovascular disease, immunity and other conditions." (PMID 33804078, 2021).
metabolic disorders (14 papers, 2013 to 2025). "The exact role of TRPV1 in metabolic disorder associated with lipid metabolism, however, is still debatable." (PMID 36589466, 2022). "In recent years, scientists have found TRPV1 plays an important role in metabolic diseases and is associated with many signaling pathways such as pancreatic secretion, glucagon signaling, inflammatory mediator regulation of TRP channels, IR, and AMPK." (PMID 35694255, 2022). "In recent years, numerous studies have demonstrated that TRPV1 plays a vital role in metabolic diseases." (PMID 35694255, 2022). "Some of these studies concluded that overexpression of TRPV1 is involved in the pathogenesis of metabolic diseases." (PMID 36589466, 2022). "Recently, TRPV1 has become a research hotspot in metabolic disorder therapy." (PMID 36589466, 2022). "Interestingly, diet-induced metabolic disorders are also alleviated by chronic use of TRPV1 agonists such as capsaicin." (PMID 36589466, 2022). "TRPV1 deletion displayed anti-inflammatory effect in murine models involving metabolism disorder." (PMID 34745416, 2021). "Recently, TRPV1 has drawn rising attention with its role in metabolic disorders." (PMID 34745416, 2021). "Therefore, chronic activation of TRPV1 has broader application potential for metabolic diseases." (PMID 40677717, 2025). "Altogether, although the target cells for evodiamine have not yet been identified, our studies strongly suggest that collaboration of multiple physiological pathways in different types of cells may be required for the beneficial effects of TRPV1 agonists in treating metabolic disorders." (PMID 23878415, 2013). "TRPV1 signaling represents a promising therapeutic target for the prevention and management of MASLD in individuals with metabolic disorders." (PMID 40864772, 2025). "Moreover, activation of TRPV1 may also contribute to enhanced metabolic function of BAT,445 possibly through mediating SIRT1/PPARγ axis, as well as controlling clock gene oscillations, indicating a protective role of TRPV1 in metabolic diseases." (PMID 37303813, 2023). "Instead, these congeners activate other receptors (e.g. peroxisome proliferator-activated receptors (PPAR)-α/γ, G-protein coupled receptors (GPR) 55, 110, 119, TRPV1 channels), which, unlike CB1, are known to counteract metabolic disorders in animal models." (PMID 32994521, 2020).